CSF1R (colony stimulating factor 1 receptor)
Diseases named in the same sentence as CSF1R in open-access papers (continued):
Sharing a sentence is not in itself a finding about the gene and the disease.
tumor (continued). "Notably, CSF-1 has autocrine and paracrine manners in the TME, which adds a new layer of CSF-1R’s tumor-promoting role in malignant tumors." (PMID 35444953, 2022). "Nevertheless, mice with CSF1R-deficient macrophages demonstrated a shift toward the M1 phenotype of pleural but not tumor macrophages." (PMID 35315360, 2022). "However, when Mir34a and Csf1r were inactivated concomitantly in IECs, the effects of single gene inactivations on tumor size and its distribution were largely neutralized." (PMID 36147476, 2022). "It was hypothesized that inhibiting CSF1R will lead to suppression of MDSCc, and therefore delayed tumor growth." (PMID 35207516, 2022). "We next evaluated if depleting TAMs with an anti–CSF-1R antibody could synergize with MNK inhibitors to control tumor growth." (PMID 35380995, 2022). "The expression of CSF-1R was higher in tumor tissues than in peritumoral tissues." (PMID 35444953, 2022). "To validate this hypothesis, we explored the role of CSF-1R in tumor immunity in TCGA cohort by dividing patients into high CSF-1R expression and low CSF-1R expression." (PMID 35444953, 2022). "The authors indicated that the TSPO PET volume increase under CSF-1R inhibition-induced GAMs depletion might result from the increase in TSPO+ tumor cell proliferation, as indicated by the simultaneously increased in [18F]FET PET volume." (PMID 35804911, 2022). "For deciphering the precise influence of tumor-associated macrophages (TAM) after X-body treatment, cells with high transcript of CD11b (ITGAM), F4/80 (ADGRE1) and CD115 (Csf1r) were defined as macrophages which accounted for nearly half of the tumor-infiltrating immune cells." (PMID 36451853, 2022). "CSF-1/CSF-1R axis promoted the differentiation of MDSCs following the tumor progression." (PMID 35585567, 2022). "Thus, CSF1R inhibition reduces M2 macrophage marker expression and impairs the tumor-promoting activity of TAMs in tumors; however, clinical studies have shown that the use of CSF1R inhibitors exerted very limited antitumor effects in patients." (PMID 36230744, 2022). "Moreover, combined inhibition of BRAF and CSF-1R, which recruits M2-polarized macrophages in a tumor, resulted in superior antitumor responses." (PMID 36246599, 2022). "Therefore, the expression levels of CSF-1R and circulating ligand are regarded as biomarkers for tumor progression, treatment failure, and poor prognosis." (PMID 35115369, 2022). "CSF1R is reported correlation with poor survival in various tumor types." (PMID 35346107, 2022). "Therefore, in this study we investigated the impact of aging and CSF-1R signaling on monocyte and macrophages in the bone marrow, spleen and in TAMs during tumor growth." (PMID 35821822, 2022). "CSF-1R has been demonstrated to be an important player in the regulation of tumor immune responses." (PMID 35444953, 2022). "The high expression of CSF1R on multiple cell types and the associated increase in Ki67+ tumor cells suggested to us that targeting the CSF1/CSF1R axis might enhance palbociclib efficacy by countering CSF1R-mediated processes." (PMID 35788566, 2022). "Similarly, pleural and tumor MC38-related TAMs were found to express less M2 Arg1 gene upon CSF1R blockade." (PMID 35315360, 2022). "Similarly to PD-L1 blockade, pretreatment with anti-CSF1R antibody reversed Lal–/– CD11c+ MDSCs’ suppressive activity on T cells and stimulation of tumor growth." (PMID 35917184, 2022). "Exogenous S-nitrosothiol administration (with S-nitrosoglutathione (GSNO)) induces S-nitrosylation of CSF1R and rescues the excess oxidation in tumor regions, in turn suppressing the tumor-promoting cytokines which are ineffectively suppressed by CSF1R blockade." (PMID 36209194, 2022). "Notably, it was determined that CSF1R blockers bound to the chemotherapeutic agents bortezomib or meflanga remarkably decrease tumor load and increase the overall survival in mice with MM tumors, compared to those treated with monotherapy alone." (PMID 35593325, 2022).
tumor (continued). "Targeting multiple kinases to simultaneously block VEGFR-, FGFR-, and CSF-1R-mediated pathways may be a more effective method of preventing tumor angiogenesis and tumor immune evasion, representing an attractive anti-cancer therapy approach." (PMID 35897702, 2022). "Furthermore, despite the reduction in tumor burden upon CSF1R blockade, there was a minimal change in the expression of AR, pERK, p-GSK, VEGF, ARV7, and Ki67." (PMID 36209194, 2022). "By targeting multiple kinases and simultaneously blocking VEGFR-, FGFR-, and CSF1R-mediated pathways, sulfatinib may prevent tumour angiogenesis and tumour immune evasion." (PMID 35408830, 2022). "Moreover, the combination of CSF-1R inhibition with CD40 agonism was able to induce potent T cell-mediated tumor killing in a melanoma model." (PMID 35205732, 2022). "Interestingly, at later stages of tumor development, bone marrow Ly6Chigh monocytes in the elderly had significantly increased intracellular CSF-1R expression compared to their younger counterparts." (PMID 35821822, 2022). "Analysis of representative genes showed that the expression of CD8a and IFN-γ genes was significantly increased while the expression of Csf1r in CD45+ tumor-infiltrating immune cells was significantly reduced in TCh3 anti-PD-L1 group compared with other groups." (PMID 35366939, 2022). "On the basis of the results of KEGG and GO, we speculate that CSF-1R may promote the development of COAD via modulating pro-tumor immune environments." (PMID 35444953, 2022). "However, splenic macrophages in young tumor-bearing mice demonstrated increased CSF-1R expression that was restricted to the intracellular compartment and not seen on the cell surface when compared to the healthy setting." (PMID 35821822, 2022). "Indeed, CSF1R suppression enabled tumor-infiltrating PMN-MDSCs to be recruited by carcinoma-associated fibroblasts." (PMID 36303138, 2022). "Therefore, blockage of endogenous CSF-1/CSF-1R signaling can inhibit EC’s tumor growth and malignant progression." (PMID 35804859, 2022). "Indeed, ectopic CSF-1 overexpression by tumor cells attenuated the trametinib-induced reduction of CSF-1R+CD11c+ MDSCs and the infiltration of activated CD8+ T cells into the TME." (PMID 35292516, 2022). "We hypothesized that the decreased tumor size observed after deletion of Csf1r in ApcMin/+ mice may be due to decreased tumor cell proliferation and increased apoptosis." (PMID 36147476, 2022). "Furthermore, intracellular CSF-1R expression increased in macrophages of elderly mice during early tumor growth but matched the levels of younger counterparts when tumors were larger." (PMID 35821822, 2022). "Most noticeably, CSF-1R expression greatly increased in vivo xenograft tumor growth." (PMID 36555673, 2022). "We found that only MES1-like tumor cells secreted CSF1 that interacted with CSF1R on TAMs." (PMID 35669791, 2022). "The CSF1-R (signaling pathway fundamental for microglia and macrophage survival) inhibition reduces GAMs’ recruitment in the tumor core, resulting in a reduction of tumor cell proliferation and invasion." (PMID 35681612, 2022). "Intracellular CSF-1R expression in these cells also increased with tumor growth." (PMID 35821822, 2022). "Others have also showed that CSF1R treatment prevent the accumulation of CD11b+Ly6C- monocytes, which recruitments is usually enhanced by radiation, limiting the pro-tumorigenic TAMs generation that supports tumor progression." (PMID 35664746, 2022). "Targeting CSF1-R can also inhibit the recruitment of MDSCs to the tumor site." (PMID 35122833, 2022). "Furthermore, we found that CSF-1R was significantly correlated with tumor-related immunosuppressive molecules (including PDCD1, CTLA4, CD80, CD86, HAVCR2)." (PMID 35444953, 2022). "CSF-1R expression, along with tumor recurrence, AJCC-stage, N-stage, and M-stage could serve as an independent prognostic factor for patients with COAD." (PMID 35444953, 2022).
tumor (continued). "Firstly, autocrine/paracrine activation of tumor cell proliferation via the M-CSF/CSF1R axis." (PMID 35677046, 2022). "Monocyte and macrophage infiltration into the tumor microenvironment may be facilitated by CSF-1/CSF-1R signaling and our previous studies indicate an expansion of TAMs in elderly vs. young mice." (PMID 35821822, 2022). "For instance, inhibiting CSF1R signaling functionally reprograms macrophage responses to enhance antigen presentation and productive antitumor T cell responses in orthotopic grafted tumor PDA models." (PMID 36256464, 2022). "Many studies demonstrated that combining chemotherapy or immunotherapy with the blockade of CSF1-R could improve anti-tumor T cell responses." (PMID 35163420, 2022). "The reduced NO level negatively influences the anti-tumor effectiveness of CSF1R blockade therapy as CSF1R at Cys224, Cys278, and Cys830 sites could not be effectively S-nitrosylated." (PMID 36209194, 2022). "Therefore, CD11c+ cells switched their functions to immune suppression and tumor growth stimulation through CSF1R/PD-L1 upregulation and metabolic reprogramming." (PMID 35917184, 2022). "In addition to a role in regulating tumor immunity, CSF-1/CSF-1R axis also plays a key role in supporting tumor cell survival, proliferation and enhancing motility." (PMID 35444953, 2022). "CSF1R inhibition triggers a compensatory PD-1/PDL1 upregulation in tumor and immune cells." (PMID 34067348, 2021). "Altogether, resistance to CSF-1R monotherapy may be explained by the cellular heterogeneity of the tumor microenvironment beyond GAMM." (PMID 34950148, 2021). "In addition to surgery, several CSF1R inhibitors including TKIs showed promising results in tumor volume decrease and reduction of debilitating symptoms." (PMID 33926503, 2021). "Similarly, CSF-1 inhibitory antibodies or pharmacological inhibition of the CSF-1/CSF-1R axis effectively blocked the recruitment of macrophages at tumor sites." (PMID 34583750, 2021). "It was observed that infiltration of MDSCs in tumor tissues increased after CSF-1R blockade, which may explain, to some extent, the limitations of the clinical efficacy of CSF-1 or CSF-1R inhibitors." (PMID 34178692, 2021). "However, CSF‐1R blockade alone usually achieves marginal therapeutic benefit, leading to the delay of tumor growth at most." (PMID 33463063, 2021). "The CSF1R inhibitor PLX3397 has shown significant anti-tumor effects in animal models, but its treatment efficacy in clinical settings remains unknown." (PMID 34248982, 2021). "The inhibition of macrophage CSF1R activity or the enhancement of STAT3 activation in the TME can promote the repolarization of M2 macrophages to a phenotype similar to M1 to overcome the immunosuppressive state that promotes tumor growth and metastasis." (PMID 34683963, 2021). "Colony-Stimulating Factor 1 (CSF1)/Colony-Stimulating Factor Receptor 1 (CSF1R) signaling orchestrates tumor-associated macrophage (TAM) recruitment and polarization towards a pro-tumor M2 phenotype, the dominant phenotype of TAMs infiltrating mesothelioma tumors." (PMID 34067348, 2021). "We hypothesize that intratumoral macrophage depletion by [89Zr]Zr-DFO-N-suc-CSF1R-mAb precluded tumor uptake higher than 89Zr-labeled control." (PMID 34976826, 2021). "No significant prognostic association was observed between CSF1R mRNA expression in the bulk tumor tissue and clinical outcomes in the TCGA cohort." (PMID 34830923, 2021). "Thirdly, we assessed CSF-1R expression on morphologically assessed tumor-associated macrophages and did not perform multiplex immunohistochemistry to confirm co-expression with other macrophage biomarkers." (PMID 34830923, 2021). "For instance, platinum- (Pt-) prodrug conjugated small particles and BLZ-945, a small molecule inhibitor of CSF-1R, not only induce apoptosis of tumor cells but also modulate the tumor immune environment to eventually augment the antitumor effect of CD8+ cytotoxic T cells through TAM depletion." (PMID 33628850, 2021).
tumor (continued). "Emactuzumab, a humanized monoclonal antibody targeting CSF1/CSF1R, inhibit tumor cell proliferation and metastasis by blocking the activity of CSF1R‐dependent TAMs, suppressing the recruitment of TAMs to the microenvironment, and enhancing the T‐cell infiltration." (PMID 34977870, 2021). "We documented that CSF1R inhibition impedes mesothelioma progression, abrogates macrophage tumor infiltration, polarizes the remaining ones towards an M1 anti-tumor phenotype and activates tumor dendritic and T cells." (PMID 34067348, 2021). "However, blockade of CSF-1R has also been shown to increase expression of key chemotactic factors that promote the influx of tumor-infiltrating lymphocytes, a finding consistent with other cancer types." (PMID 34976006, 2021). "However, in syngeneic tumor models, anti-CSF-1R treatment also depleted TAMs, suggesting either similarities between tissue-resident macrophages and TAM populations or a common cellular origin of these two populations." (PMID 33924237, 2021). "Specifically, these mutations are located on five tumor suppressors (SDHA, RB1CC1, PTCH1, DMBT1, BCR) and eight proto-oncogenes (MERTK, CSF1R, MYB, ROS1, PCM1, FGFR2, MYH11, BRCC3) and have an allele frequency lower than 0.01 in the Genome Aggregation Database (GnomAD)." (PMID 33466296, 2021). "Comprehensively analyzing the tumor–immune interactions in the tumor microenvironment would enable us to understand of the mechanism mediating the different clinical outcome between patients with different CSF1R genotypes." (PMID 34830445, 2021). "Moreover, we analyzed the phenotype of tumor-infiltrating T cells in Flk-1fl/fl and Csf1r-Cre+Flk-1fl/fl TB mice." (PMID 34673569, 2021). "In a later study, colony stimulating factor-1 receptor silencing siRNA was co-delivered with PI3K inhibitor, BEZ-235 using an M2 tumor-associated macrophage targeting nanomicelle to elicit therapeutic immune responses against pancreatic cancer cells both in vitro and in tumor models." (PMID 34683931, 2021). "Efforts to deplete macrophages using small molecule inhibitors of the CSF-1/CSF-1R axis led to the unexpected finding that targeted populations could be instead repolarized towards anti-tumor phenotypes." (PMID 33924237, 2021). "However, the discovery of selective CSF-1R inhibitors devoid of type III kinase activity has proven to be challenging in tumor treatment." (PMID 34729112, 2021). "In addition, cancer patients with CSF1R c.1085A>G variant had less tumor-associated macrophages, M2-like macrophages, and VEGF expression in tumor tissues." (PMID 34830445, 2021). "Indeed, studies in various solid malignancies have shown that blockade of the axis with monoclonal antibodies or CSF-1R inhibitors can lead to reduced myeloid numbers at the tumor site and increased numbers of macrophages with antitumor activity." (PMID 33917501, 2021). "Likewise, in the clinic, CSF1R inhibition has led to robust macrophage depletion in both normal tissues and solid tumors; however, minimal anti-tumor efficacy has been observed." (PMID 33511454, 2021). "Additionally, there was a reduction in CD163+CSF1R+ macrophages in tumor tissue and increased CD8:CD4 ratio in response to treatment." (PMID 34868044, 2021). "Similarly, the RUNX1/CSF-1R/IL-34 axis was responsible for the tumor rebound in BRAF inhibitor resistant melanoma." (PMID 33408768, 2021). "Having observed that the mesothelioma-limiting effects of CSF1R inhibitor might more likely occur as a result of its effect on tumor milieu, we focused on myeloid populations that are prevalent in mesothelioma tumors and affected by CSF1R signaling." (PMID 34067348, 2021). "This was driven by radiation-induced expression and secretion of CSF-1 that, when blocked with small molecule inhibitors of the CSF-1 receptor (CSF-1R), markedly reduced the expansion of myeloid cells and enhanced the response of the irradiated tumour to radiation." (PMID 34299373, 2021).
tumor (continued). "However, the reported effects of CSF1R inhibitor therapy on the inflammatory state of the tumor microenvironment (TME) and tumor growth vary widely." (PMID 33511454, 2021). "Having seen that CSF1R blockade successfully limited immune-suppressive myeloid populations, we subsequently examined whether it affected tumor lymphocytes." (PMID 34067348, 2021). "We observed that the enhancement of combined IT with anti-CSF-1R did not cause any significant changes in tumor infiltration with immune cells (CD45+) in both TC-1/A9 and TC-1/dB2m tumors." (PMID 34205330, 2021). "Finally, blocking CSF1R in vivo inhibits monocyte recruitment into the tumor environment, leading to MΦ depletion." (PMID 34771453, 2021). "In addition, previous studies have identified potential markers (such as CSF1R) for the reprogramming of GAMs; however, it acquired resistance over time and resumed vigorous tumor growth." (PMID 33607293, 2021). "Accordingly, in vitro and in vivo studies have demonstrated that inhibition of CSF-1R might restore the CD8+ T cell anti-tumor response." (PMID 34830817, 2021). "Of interest, IGF-1 can increase activity of the PI3K pathway found in CSF-1R-resistant tumor cells." (PMID 34949203, 2021). "Furthermore, CSF-1/CSF-1R signaling contributes to the conversion of TAMs from a tumor-suppressor phenotype to a tumor-promoter phenotype." (PMID 34178692, 2021). "Interestingly, it has been reported that anti-CSF-1R therapy had only minimal impact on the intratumoral accumulation of engineered T cells and even interfered with their anti-tumor activity." (PMID 33503832, 2021). "NK cells may control the seeding of circulating tumor cells due to crosstalk with myeloid cells, a process that is affected when tumors are treated with depleting CSF1R antibodies." (PMID 33953710, 2021). "The mRNA expression of C1QC, CSF1R, LAPTM5 and SLCO2B1 was negatively associated with tumor purity." (PMID 33428598, 2021). "CRCs with CSF1R c.1085 genotype A_G contained less M2-like macrophage infiltrates in tumor tissues." (PMID 34830445, 2021). "Interestingly, CSF1R inhibition as monotherapy resulted in improved survival and even tumor regression, accompanied by re-education of TAMs into a rather antitumor phenotype." (PMID 34539650, 2021). "Increased expression of PD-L1 and CTLA-4 on tumor cells, following inhibition of the CSF-1R signaling, may partially account for the observed synergy." (PMID 33503832, 2021). "Furthermore, the tumor-associated microenvironment, including macrophages expressing the receptor CSF1R, promote and nourish tumor cells." (PMID 34063518, 2021). "However, due to CSF-1R being involved in multiple biological processes, specific tumor therapies against CSF-1R have generated undesirable side effects." (PMID 33408768, 2021). "CSF-1R inhibition combined with CD40 agonism is synergistic in various murine tumor models." (PMID 33804039, 2021). "Consequently, targeting CSF-1R produced less invasive tumours with clearly delineated borders, thus illustrating a synergistic interaction between tumour cells and GAMs." (PMID 33803414, 2021). "While CSF1R inhibitors and CD40 agonists potently reduce tumor growth in mice, the combined use of Emactuzumab (anti-CSF1R monoclonal antibody) with Selicrelumab (agonistic CD40 monoclonal antibody) in patients with metastatic PDAC has not translated into objective clinical responses (NCT02760797)." (PMID 34201127, 2021). "We evaluated the role of CSF1/CSF1R axis blockade in tumor-infiltrating immune subsets." (PMID 34067348, 2021). "Moreover, components of the CSF1/CSF1R axis are highly expressed in gastric cancer and promote tumor proliferation and migration." (PMID 33406733, 2021). "It has been previously reported that inhibition of CSF1R in macrophages may lead to a reprogramming of macrophages, reducing tumor growth." (PMID 33607293, 2021).